BDNF (brain derived neurotrophic factor)
Diseases named in the same sentence as BDNF in open-access papers (continued):
Sharing a sentence is not in itself a finding about the gene and the disease.
tumor (continued). "There is now extensive literature demonstrating that BDNF/TrkB signaling is involved in regulating several aspects of tumor cell physiology, including neovascularization, tumor proliferation, epithelial-to-mesenchymal transition, apoptosis resistance, and cytotoxic drug resistance." (PMID 34777634, 2021). "Moreover, miR-107 can inhibit tumor growth and metastasis through targeting brain-derived neurotrophic factor (BDNF)/PI3K/AKT axis in human non-small lung cancer." (PMID 33849540, 2021). "In this context, ACD may contribute to overall tumor growth by generating heterogeneous populations of cells that form a mutually beneficial paracrine network involving BDNF, a p75NTR ligand." (PMID 33351787, 2021). "Moreover, glioma-bearing mice reared in an enriched environment (EE) showed enhanced levels of BDNF together with significantly reduced tumor growth, suggesting a pivotal role for this neurotrophin in glioma proliferation." (PMID 34690699, 2021). "Inactivating BDNF-mediated PI3K/Akt signaling pathway activation could increase expression of miR-496 which was regarded as suppress tumor growth." (PMID 34818353, 2021). "Furthermore, rescue experiments demonstrated that BDNF overexpression essentially reversed the anti-tumor effects mediated by miR-489-3p re-expression on GBM cells." (PMID 33817216, 2020). "Both NGF and BDNF have already been shown to promote tumor innervation in other tissues." (PMID 32155948, 2020). "All these results suggest that miR-489-3p might exert anti-tumor effects in GBM by inactivating the PI3K/AKT signaling pathway through BDNF." (PMID 33817216, 2020). "BDNF plays a vital part in elevating the ability of tumor metastasis and proliferation." (PMID 33015172, 2020). "BDNF and TrkB are upregulated in cancers and promote tumor progression." (PMID 32471985, 2020). "We explored the roles of BDNF in circHIPK3/miR-107-mediated tumor progression in NSCLC." (PMID 33015172, 2020). "Besides the well characterized angiogenic effect of some tumor-derived factors; others, such as BDNF, recruit peripheral nerves and leukocytes." (PMID 32555170, 2020). "We highlighted circHIPK3/miR-107/BDNF as a novel tumor screening biomarker for NSCLC." (PMID 33015172, 2020). "The release of neurotransmitters—such as catecholamines and acetylcholine—by nerves into the vicinity of cancer and stromal cells, along with the secretion of neurotrophic growth factors such as NGF and BDNF, and miRNAs by cancer cells, drives the crosstalk that ultimately enables tumor progression." (PMID 33322770, 2020). "Studies have shown that several types of cancer overexpress neurotrophins such as NGF and BDNF, which might contribute to tumor progression and angiogenesis." (PMID 31608227, 2019). "Taken together, comparison of BDNF growth factor and NTRK2 receptor gene expression with clinical data revealed that BDNF is produced both in stroma and in tumor cell nests of HNSCC, the availability of the NTRK2 gene product, TrkB, is limited to approximately 40% of the cases." (PMID 30641914, 2019). "Furthermore, they claim CAF and tumor cell interaction to be responsible for lymphovascular metastasis and mechanistically demonstrate the critical importance of BDNF-TrkB signaling in this process." (PMID 30641914, 2019). "In addition, high adrenergic catecholamines levels promote NGF and BDNF secretion favoring tumor innervation, ensuing further adrenergic signaling in a feed forward loop that promotes tumor growth." (PMID 31248001, 2019).
tumor (continued). "In our hypothesis, BDNF might be a factor with similar function as TGF-β1 in influencing the separation of disseminating tumor cell groups but it is extended also by cell survival support functions." (PMID 30641914, 2019). "Here, we present the correlation between the expression levels of TRKB and/or its secreted ligand, brain-derived neurotrophic factor (BDNF), and clinicopathological characteristics, especially regarding tumor differentiation, tissue invasion, and disease-free survival in patients with OSCC." (PMID 29861866, 2018). "We also demonstrated high expressions of these proteins in neo-vessels of both HSC-4 and HSC-3 cell-derived tumors in the mouse transplantation model systems (data not shown), raising the possibility that OSCC tumor cells secreting BDNF are able to induce tumor angiogenesis." (PMID 29861866, 2018). "Our data suggest that the BDNF/TRKB signaling pathway may mediate OSCC tumor progression, especially multiple behaviors of aggressive MD/PD-OSCC tumor cells." (PMID 29861866, 2018). "Moreover, the TRKB inhibitor selectively blocked BDNF-induced tumor cell proliferation and migration accompanied with the suppression of TRKB phosphorylation in PD-OSCC but not in WD-OSCC in vitro." (PMID 29861866, 2018). "From our study, the analysis of the relationship between 2-year disease-free survival and high expression of TRKB/BDNF showed significantly higher rates of tumor recurrence in patients with TRKBhigh and/or BDNFhigh OSCC than in those suffering from TRKBlow/BDNFlow OSCC." (PMID 29861866, 2018). "The decreased expression of ERK1/2, NPAS4, and BDNF are also seen in neurodegenerative conditions and aging, and may constitute an important tumor brain mechanism." (PMID 29556248, 2018). "Next, we investigated whether tumor differentiation was correlated with the expression levels of TRKB and BDNF, using these tumor cell lines." (PMID 29861866, 2018). "The BDNF/TRKB signaling pathway mediates tumor cell growth, migration, and invasion." (PMID 29861866, 2018). "Taken together, these data suggest that the BDNF/TRKB signaling pathway may regulate tumor progression in poorly differentiated OSCC." (PMID 29861866, 2018). "We next tested the hypothesis that modulation of BDNF in the CAF compartment would profoundly impact MMP-9 activity in the tumor compartment." (PMID 28966935, 2017). "To determine whether the effects of CAFs on HNSCC cells in the tumor microenvironment were directly attributable to CAF-secreted BDNF, we performed BDNF rescue experiments under in vitro conditions." (PMID 28966935, 2017). "We therefore hypothesized that the CAF-induced alterations in HNSCC behavior was due, in part, to CAF-secreted BDNF in the tumor microenvironment." (PMID 28966935, 2017). "As such, successful chemotherapy leads to a reduced tumor load, which by itself may affect BDNF levels." (PMID 29179434, 2017). "Furthermore, it would be important to establish and compare the roles of tumor growth and chemotherapy in BDNF regulation, and analyze BDNF regulation as a function of malignant tumor load." (PMID 29179434, 2017). "Consistent with this, our patient-derived tumor specimens showed BDNF expression in astrocytes in the peritumoral region, whereas we saw similar levels of intracellular BDNF in all examined tumor-derived and non-tumor cell lines (BBM1, 361, astrocytes, and fibroblasts)." (PMID 28446206, 2017). "We suggest that BDNF may serve as a promising therapeutic target for the restriction of VEGF-C-mediated tumor lymphangiogenesis and lymphatic metastasis." (PMID 28771226, 2017). "The wound scratch assay revealed significant impairment of HNSCC migration under conditions of BDNF knockdown in the CAF-CM, suggesting that potentiation of cellular motility is due in part to paracrine communication between tumor and stromal cells through BDNF-TrkB." (PMID 28966935, 2017).
tumor (continued). "Additionally, this degree of impairment closely approximated the effects of stimulation with CM-NF, suggesting that upregulation of BDNF expression in CAFs was in part responsible for the hyperdynamic behavior of tumor cells." (PMID 28966935, 2017). "Our previous clinical study showed that BDNF in the brain acts as an effector of transcription of immediate-early genes that are expressed as a response to eustress, which is thought to enhance the chemosensitivity of tumor cells." (PMID 27852063, 2016). "BDNF was detected in all seven samples, involving, on average, 41.5% of imaged tumor cells." (PMID 27145455, 2016). "BDNF and its TrkB receptor are known to protect tumor cells from chemotherapy-induced cell death." (PMID 27852063, 2016). "Some studies have shown that tumor cells treated with BDNF are less sensitive to cytotoxic drugs." (PMID 27145455, 2016). "Given that the dysregulation of miR-191 and BDNF levels vary among different tumor types, regulatory cofactors may determine whether miR-191 suppresses or activates the expression of BDNF." (PMID 25601223, 2015). "An anti-BDNF treatment in xenografted mice resulted in tumor growth inhibition." (PMID 25036590, 2014). "Tumor samples lacking SFRP1 protein expression also exhibited loss of BDNF protein expression and vice versa." (PMID 25036590, 2014). "BDNF stimulates tumor cell invasion; it was found to be overexpressed in adenoid cystic carcinoma." (PMID 25408713, 2014). "Furthermore, BDNF was shown to be expressed in several tumor types such as breast cancer, lung cancer, colon cancer, hepatocellular carcinoma, and head and neck squamous cell carcinoma." (PMID 23892595, 2013). "Accumulating evidences indicate that BDNF may act as an angiogenic factor in normal and tumor tissues." (PMID 24403258, 2013). "In addition, transfection of cells with β5 integrin siRNA significantly abolished BDNF-mediated cell migration, suggesting that β5 integrin is crucial to mediating the function of BDNF in tumor cell migration." (PMID 23874483, 2013). "Moreover, of the 110 tumor samples analyzed, a strong correlation was noted (r = 0.597, p<0.01) between the expression of TrkB and its secreted ligand, BDNF, further supporting a potential role for this pathway." (PMID 23936232, 2013). "In addition, the BDNF/TrkB pathway is reported to have a critical role in tumorigenesis as it promotes proliferation, differentiation, angiogenesis and tumor invasiveness." (PMID 23285024, 2012). "Our previous study also demonstrated that inhibition of BDNF in RPMI8226 could decrease tumor burden in SCID mice subcutaneously injected with MM cells." (PMID 23077504, 2012). "Thus it is possible that antisense inhibition of BDNF abolished the direct promotion of BDNF on tumor growth." (PMID 23077504, 2012). "It was demonstrated BDNF/TrkB protected various tumor cells from apoptosis." (PMID 21999199, 2011). "BDNF is a cytokine secreted by a few human cancers, supporting growth and survival of tumor cells." (PMID 21999199, 2011). "Despite the increasing evidence of BDNF and TrkB on tumor progression, whether they are involved in multiple HCC has not yet been determined." (PMID 21999199, 2011). "In the present study, we showed that BDNF and TrkB (both forms) were overexpressed in tumor tissue in comparison either to each corresponding non-tumor tissue from the same patient or to the control tissues with benign disease." (PMID 21966426, 2011). ",84NGF, and NEUROD1 expression in tumor spheres and tumor-like cells suggests autocrine signaling aiding tumor survival, while BDNF expression in normal slices suggest potential paracrine signaling mechanisms that may contribute to tumor cell migration and survival." (PMID 40917877, 2025). "Accordingly, SKM muscle-derived BDNF may act locally to inhibit tumor growth." (PMID 38928185, 2024).
tumor (continued). "Thus, F3.CD-TK displayed a coculture profile (i.e., lower VEGF and higher BDNF) that could be more effective in concomitantly tracking/controlling tumor cells and enhancing neural recovery." (PMID 39329707, 2024). "Besides, BDNF/TrkB signaling may regulate tumor-induced facial hypersensitivity in oral cancer pain." (PMID 39906323, 2024). "MiR-496 has diminished expression in a wide range of NSCLC cells, and researchers have experimentally demonstrated that overexpression of miR-496 could inactivate the BDNF (a brain-derived neurotrophic factor)-mediated PI3K/Akt signaling pathway to inhibit tumor growth." (PMID 38169723, 2023). "Therefore, it can be speculated that NCOR2 may affect the biological function of tumour cells by regulating the expression of BDNF through NR4A1." (PMID 36497280, 2022). "Moreover, DNA methylation plays a regulatory role for BDNF and MSTN, lower methylation levels may cause an abnormal increase of BDNF and MSTN in tumor samples." (PMID 36733390, 2022). "Consequently, increased expression of BDNF might lead to the migration of immune cells to tumor tissues." (PMID 34777634, 2021). "Similarly, an association of VEGF-C and BDNF with solid tumours is not surprising since tumour microenvironment remodelling with vascular growth aids in the growth and maintenance of solid tumours while being less pronounced in haematological malignancies." (PMID 34830872, 2021). "An explanation for this is that tumor staging and metastasis may affect the serum BDNF level." (PMID 33628340, 2021). "Thus, in patients with PC, the serum BDNF concentration appeared to be associated with tumour removal, because it did not significantly change when cancer tissue was not removed." (PMID 34395067, 2021). "Thus, the inhibitory activity of LicA may be seen generally in tumor cells which overexpress TrkB and BDNF." (PMID 31941116, 2020). "For example, miRNA-210 targeting BDNF, miRNA-21 modulating microglia, and miRNAs −27a and −132 modulating Tau would contribute to enlightening what pathway triggers a neuron to transform into an undifferentiated and immortal tumor cell or deteriorated dying cells." (PMID 33328891, 2020). "Moreover, brain-derived neurotrophic factor (BDNF) is a very interesting NTF in the tumor context." (PMID 30123112, 2018). "To directly test the hypothesis that an active CAF-derived BDNF axis specifically regulates the oncogenic milieu, we pharmacologically and genetically inhibited BDNF signaling and interrogated the biological response of the tumor compartment in vitro." (PMID 28966935, 2017). "While in certain disease models, tumor-derived BDNF instigates abnormal intracellular pathway upregulation in an autocrine and paracrine manner, whether CAF-derived BDNF ligand contributes to a putative CAF-tumor synapse in potentiating lymphovascular invasion has not been explored to date." (PMID 28966935, 2017). "In conclusion, we have demonstrated that BDNF/TrkB signaling in tumor tissues is associated with tumor progression and poor prognosis in CRC patients, and that it is also associated with proliferation, migration, invasion, and anoikis resistance in BDNF/TrkB co-expressing CRC cells." (PMID 24801982, 2014). "BDNF knockdown may inhibit tumor invasion of HepG2 and HCCLM3 cells." (PMID 23531103, 2013). "Studies have shown that SCs can specifically activate receptor tyrosine kinase family members on the surface of tumor cells (including the RET, TrkA, TrkB) by secreting GDNF, NGF, and BDNF." (PMID 41583906, 2026). "The polymeric immunoglobulin receptor (pIgR) mediated IgA transcytosis also contributed to the tumor control, as pIgR knockout reduced BDNF and TSPAN7 IgA mediated tumor control." (PMID 40356924, 2025). "Transcriptome analysis showed upregulation of brain‐derived neurotrophic factor (BDNF), semaphorin 7A (SEMA7A), and plexin‐B2 (PLXNB2) in SUDHL6‐EBV derived tumor tissues." (PMID 40488319, 2025).
tumor (continued). "The MMP-3 was found to be more expressed in healthy stroma compared to tumor stroma, and MMP-2 was more expressed in T cell tumors compared to B cell tumors, a similar result to BDNF." (PMID 40427122, 2025). "Neurotrophic factors (e.g., NGF, BDNF, GDNF) and axon guidance molecules (e.g., semaphorins, netrins, ephrins) mediate this integration, promoting neural remodeling and facilitating tumor innervation." (PMID 41009819, 2025). "Neuronal secretions—including NGF, BDNF, CGRP, norepinephrine, and neuronal substance P—serve as potent mediators of tumor–nerve interactions." (PMID 41009819, 2025). "This includes studying the role of exercise‐induced factors like brain‐derived neurotrophic factor (BDNF) and their influence on neuroplasticity and tumor suppression." (PMID 40792048, 2025). "Tumor innervation can be induced by cancer cells through the secretion of neurotrophins such as nerve growth factor (NGF), brain-derived neurotrophic factor (BDNF) and glial cell-derived neurotrophic factor (GDNF), amongst others." (PMID 40075699, 2025). "The first prerequisite for clinical progress is molecular stratification that distinguishes tumours driven by ligand-dependent NGF-TrkA, BDNF-TrkB or GDNF–RET loops from those harbouring activating rearrangements or kinase-domain point mutations." (PMID 41142827, 2025). "This in turn activates the PKA and ERK signaling pathways, promoting tumor cell proliferation, transformation, and the secretion of neurotrophic factors such as NGF or BDNF." (PMID 38567163, 2024). "In ESCC and GC, TrkB is overexpressed and plays a role in tumor growth, metastasis, and EMT via the BDNF/TrkB pathway." (PMID 38081962, 2024). "Western blotting also showed a decreased level of BDNF and TrkB expression in TNFR2 KO xenograft tumor tissue." (PMID 38592583, 2024). "Consistent with the reduced tumor growth and SCZ-like behaviors, the levels of TrkB and BDNF expression were significantly decreased in the lung tumor tissues and pre-frontal cortex of TNFR2 knockout mice." (PMID 38592583, 2024). "Mounting evidence suggests that malignant cells influence the tumor microenvironment (TME) by releasing a plethora of neurotrophic factors, e.g. NGF, BDNF, GDNF, Neuturin and Ephrin B1 to promote axonogenesis, neurogenesis and neural reprogramming." (PMID 39592661, 2024). "This anti-tumor effect is attributed to the EE-induced increase in BDNF and is manifested through enhanced function of CD8 cytotoxic T lymphocytes (CTL), which play a central role in anti-tumor immunity." (PMID 38721229, 2024). "TrkB, a receptor tyrosine kinase for brain-derived neurotrophic factor (BDNF), also disrupts TGF-β1’s tumor suppressor activity in various cancers." (PMID 38675493, 2024). "Research shows that cancer cells express neurotrophic markers such as NGF, GDNF, and brain‐derived neurotrophic factor (BDNF), releasing axon‐guiding molecules that promote axonogenesis and attract nerves to the tumor site." (PMID 39492832, 2024). "BDNF can bind to TrkB receptors to activate ERK/CREB, PI3K/AKT, and NF‐kB pathways, ultimately enhancing tumor survival, proliferation, and migration." (PMID 39036344, 2024). "Overexpression of neurotrophic growth factors, such as NGF and brain-derived neurotrophic factor (BDNF), in tumor and stromal cells promotes cancer innervation." (PMID 38233872, 2024). "This communication involves the exchange of signals mediated by brain-derived neurotrophic factor (BDNF) and NLGN3 proteins, which contribute to tumor growth and survival." (PMID 38732975, 2024). "The expression and rapid release of NRG1 in neurons and their axons can be stimulated by NGF, BDNF, NT-3, and GDNF, which are extremely abundant in tumor microenvironment." (PMID 36900158, 2023).